FOXA2 (forkhead box A2)
Diseases named in the same sentence as FOXA2 in open-access papers (continued):
Sharing a sentence is not in itself a finding about the gene and the disease.
Autoimmunity (1 paper, 2018). The occurrence of an immune reaction against the organism's own cells or tissues. "Thus, the Foxa1 and Foxa2 transcription factors are important to our understanding of autoimmunity through their roles both in TEC and Treg function." (PMID 30061015, 2018). "It would in the future be interesting to assess the consequences of increased Treg in Foxa1/2Foxn1cKO mice model on induction of autoimmunity and to investigate the clinical significance of the function of FOXA1 and FOXA2 in human TEC." (PMID 30061015, 2018). "Thus, Foxa1 and Foxa2 in TEC promote positive selection of CD4SP T-cells and modulate regulatory T-cell production and activity, of importance to autoimmunity." (PMID 30061015, 2018).
Cerebral ischemia (1 paper, 2024). Restriction of arterial blood supply to the brain associated with insufficient oxygenation to support the metabolic requirements of the tissue. "Role of Baicalein in Neuroprotection: The research shows that baicalein alleviates cerebral ischemia-reperfusion injury by upregulating SIRT6 expression, promoting FOXA2 deacetylation, and ultimately inhibiting ferroptosis." (PMID 39299807, 2024).
chronic rhinosinusitis (1 paper, 2022). Chronic form of sinusitis. "FOXA2 is negatively correlated with IL-6 in patients with chronic rhinosinusitis." (PMID 36505412, 2022).
cleft palate (1 paper, 2021). Cleft palate is a fissure type embryopathy that affects the soft and hard palate to varying degrees. "This comprehensive analysis revealed decreases in gene expressions associated with lung development; Foxa2, Notch1, Foxp2, Nkx2.1, and intestine development; Cdx2, Foxf2, Foxl1, and skeletal development; Hoxd12, Hoxd13, Scx, Brachyury, and cleft palate; Foxf2." (PMID 34671097, 2021).
colitis (1 paper, 2023). Inflammation of the colon. "To confirm the role of FOXA2 in CRC, we established a colitis‐associated CRC mouse model using intestinal epithelial cell‐specific FOXA2 knockout (FOXA2cKO) mice." (PMID 37875418, 2023).
Coronary Heart Disease (1 paper, 2022). "This is the first time that FOXA2 gene methylation has been found in postmenopausal women with coronary heart disease." (PMID 36032780, 2022). "Finally, we employed methylation-specific PCR to demonstrate that FOXA2 was methylated at a high level in postmenopausal women with coronary heart disease." (PMID 36032780, 2022).
dermatomyositis (1 paper, 2020). Dermatomyositis (DM) is a type of idiopathic inflammatory myopathy characterized by evocative skin lesions and symmetrical proximal muscle weakness. "It is tempting to speculate that certain autoimmune myositis disorders such as polymyositis or dermatomyositis, or other forms of musculoskeletal painful diseases could one day be mitigated or treated via an approach that upregulates FoxA2 activity in the muscles." (PMID 32143325, 2020).
diabetes insipidus (1 paper, 2012). A disorder characterized by excretion of large amounts of urine, accompanied by excessive thirst. "Hence, Foxa1, but not Foxa2, is expressed in the kidney and, when deleted, causes nephrogenic diabetes insipidus." (PMID 22737085, 2012).
endometrial tumor (1 paper, 2022). "We also found evidence for a role of Foxa2 in EMT suppression in organoids derived from Foxa2/Pten primary mouse endometrial tumors; for example, Foxa2 reexpression caused decreased growth and striking loss of both cellular organization and pseudopodial extensions." (PMID 35703180, 2022). "By integrating results from our cell lines, organoids, animal models, and patient data, our findings demonstrated that FOXA2 is an endometrial tumor suppressor associated with aggressive disease and with shared commonalities among its roles in endometrial function and carcinogenesis." (PMID 35703180, 2022). "Taken together, these results showed that FOXA2 functions as a multitasking endometrial tumor suppressor by regulating the transcriptome through shaping the enhancer landscape." (PMID 35703180, 2022). "Furthermore, the results validated this animal model for further investigations of FOXA2 as an endometrial tumor suppressor." (PMID 35703180, 2022). "This striking cancer phenotype occurred only with simultaneous inactivation of Pten (which by itself resulted only in the formation of noninvasive/nonlethal hyperplasias), establishing potent synergism between Foxa2 and this canonical endometrial tumor suppressor." (PMID 35703180, 2022).
endometrioid adenocarcinoma (1 paper, 2022). An adenocarcinoma characterized by the presence of malignant glandular epithelial cells resembling endometrial cells. "A subsequent study specifically evaluating FOXA2 reported an endometrioid adenocarcinoma mutation rate of 9.4%, with a spectrum of mutations again interpreted as consistent with a tumor suppressor role." (PMID 35703180, 2022). "Thus, histologically, the Foxa2/Pten tumors resembled well-differentiated (i.e., grade 1) human endometrioid adenocarcinomas." (PMID 35703180, 2022).
ependymoma (1 paper, 2022). A WHO grade II, slow growing tumor of children and young adults, usually located intraventricularly. "The SHH-2 gene signature comprised ALDH1A2 and EN2, which are involved in the organization of the hindbrain and upregulated in ependymoma PFA2 tumors, as well as the dopaminergic neuron markers FOXA1 and FOXA2." (PMID 35501487, 2022).
esophageal squamous cell carcinoma (1 paper, 2021). Esophageal squamous cell carcinoma (ESCC) is a type of esophageal carcinoma (EC) that can affect any part of the esophagus, but is usually located in the upper or middle third. "It has been reported that Forkhead transcription family member (FOXA2) regulates esophageal squamous cell carcinoma (ESCC) progression." (PMID 34551777, 2021).
female infertility (1 paper, 2022). Diminished or absent ability of a female to achieve conception. "Uterine conditional depletion of Foxa2 causes loss of leukemia inhibitory factor (LIF) secretion and female infertility." (PMID 35861728, 2022).
gastric tumors (1 paper, 2018). "Expression of FOXA2, on the other hand, was shown to suppress gastric tumors, suggesting its role in gastric oncogenesis." (PMID 29720137, 2018).
germinoma (1 paper, 2020). A malignant germ cell tumor arising in the central nervous system. "While this particular sample showed higher expression of GATA6, FOXA2, or HNF4A and hypermethylation of RASSF1, RUNX3, HIC1, or APC, its methylation pattern was partially common to that of germinomas or ECs." (PMID 32999426, 2020).
hepatoid adenocarcinoma (1 paper, 2025). An adenocarcinoma with morphologic characteristics similar to hepatocellular carcinoma, arising from an anatomic site other than the liver. "Adenocarcinomas are generally negative for these markers, with the exception of hepatoid adenocarcinoma, which is FOXA2-positive." (PMID 41230344, 2025).
hyperinsulinemic hypoglycemia (1 paper, 2010). An inherited autosomal recessive syndrome characterized by the disorganized formation of new islets in the pancreas and congenital hyperinsulinism. "Moreover, ablation of the forkhead transcription factor Foxa2 in mice induced hyperinsulinemic hypoglycemia in parallel with a 3-fold increase in CgB mRNA." (PMID 20126668, 2010).
hyperlipidemia (1 paper, 2022). "Among these hyperlipidemia-associated five loci, a mechanism has been established for only rs780092 (2p23.3), owing to LD with rs780094 (r2 = 0.45 in EAS of the 1000 Genomes Project); rs780094 facilitates the binding of transcription factor FOXA2 to regulate GCKR expression." (PMID 35046404, 2022).
hypertrophic cardiomyopathy (1 paper, 2013). A condition in which the myocardium is hypertrophied without an obvious cause. "The present results showed that many genes significantly altered in cell development and hypertrophic cardiomyopathy by overexpressed atrogin-1, Myh6, Serca2 (ATP2A2) and Prkcz were significantly up-regulated, whereas Itga3 (also known as CD49c) and Foxa2 were down-regulated.." (PMID 23335977, 2013).
Hypoinsulinemia (1 paper, 2015). A decreased concentration of insulin in the blood. "In non-ruminant liver, hypoinsulinemia due to undernutrition increases NEFA flux into liver where they activate PPARα and forkhead box A2 (FOXA2) resulting in an overall increase in fatty acid oxidation and ketogenesis." (PMID 26451842, 2015).
idiopathic pulmonary fibrosis (1 paper, 2015). Idiopathic pulmonary fibrosis (IPF) is a nonneoplastic pulmonary disease that is characterized by the formation of scar tissue within the lungs in the absence of any known cause. "Allele-specific transactivation of the MMP7 gene by the FOXA2 transcription factor was observed in idiopathic pulmonary fibrosis patients." (PMID 25658610, 2015).
intrahepatic cholangiocarcinoma (1 paper, 2019). A carcinoma that arises from the intrahepatic bile duct epithelium in any site of the intrahepatic biliary tree. "Currently, very few studies have investigated the role of FOXA2 expression in intrahepatic cholangiocarcinoma." (PMID 31689237, 2019). "In this study, we found that the expression of FOXA2 was significantly decreased in intrahepatic cholangiocarcinoma (ICC) in 41.2% of all patients." (PMID 31689237, 2019). "We constructed FoxA2 conditional-knockout mice using the same strategy and generated a TAA-induced intrahepatic cholangiocarcinoma model." (PMID 31689237, 2019).
laminopathy (1 paper, 2018). A rare genetic disorder caused by mutations in genes encoding proteins of the nuclear lamina. "We found that Foxa2 occupancy is also increased in Zmpste24 mutant mice, a laminopathy model, connecting our findings to Foxa2 binding in old livers." (PMID 29484800, 2018). "We also show that Foxa2 binds more sites in Zmpste24 mutant mice, a progeroid laminopathy model, similar to increased Foxa2 occupancy in old livers." (PMID 29484800, 2018).
Miscarriage (1 paper, 2021). A pregnancy that ends at a stage in which the fetus is incapable of surviving on its own, defined as the spontaneous loss of a fetus before the 22th week of pregnancy. "Furthermore, mice with a heterozygous knockout of FOXA2 had an elevated miscarriage rate because of abnormal blastocyst implantation and decidualization, similar to the phenotype of RPL." (PMID 34925444, 2021). "We identified FOXA2 as a new candidate gene with variants causing RPL, and a subset of genes that might be associated with miscarriage." (PMID 34925444, 2021).
mucinous tumors (1 paper, 2021). "Finally, RNA expression of differentiation marker FOXA2 and CSC marker ETV1 was higher in PDS derived from mucinous tumors compared to PDS derived from epithelial tumors." (PMID 33356003, 2021).
myocardial infarction (1 paper, 2025). Gross necrosis of the myocardium, as a result of interruption of the blood supply to the area, as in coronary thrombosis. "ISL1+ MESP1+ FOXA2+ stem cell clones isolated from neonatal cardiovascular tissue represent a novel resource of cells with the capacity to restore cardiac function following myocardial infarction in a preclinical large animal model." (PMID 41561127, 2025). "Comparable ISL1+ MESP1+ FOXA2+ stem cell clones were then isolated from sheep for functional analysis in a sheep model of myocardial infarction and allogeneic stem cell-based repair without immunosuppression." (PMID 41561127, 2025).
neuroendocrine carcinoma (1 paper, 2024). A malignant neuroendocrine neoplasm composed of cells containing secretory granules that stain positive for NSE and chromogranin. "Antibody array protein chip analysis of transcription factors in 3DiNET ORION cells revealed expression of several intracellular transcription factors involved in neuroendocrine cancer pathobiology—Snail, GATA4, FoxA2, Sox-2, PDX-1 and E-cadherin." (PMID 39103560, 2024). "Protein array analysis showed expression of multiple intracellular transcription factors involved in neuroendocrine cancer pathobiology—Snail, GATA4, FoxA2, Sox-2, PDX-1 and surface molecule (E-cadherin)." (PMID 39103560, 2024).
nonalcoholic fatty liver disease (1 paper, 2023). "This study aims to investigate the mechanism by which Foxa2 affects nonalcoholic fatty liver disease (NAFLD)." (PMID 38084145, 2023).
pyometra (1 paper, 2024). "The ectopic expression of FOXA2 in the endometrium of CLCa KO mice and the further expression of K14 in these mice that develop pyometra indicates abnormality of the epithelial lumen." (PMID 37923360, 2024). "All the CLCa KO mice showed exogenous FOXA2 expression in their endometrial epithelium and only some pyometra-affected mice showed the K14 expression phenotype." (PMID 37923360, 2024). "Ectopic expression of FOXA2 was observed in epithelial cells at the uterine lumen of CLCa KO animals with pyometra and also, to a lesser extent, in the CLCa KO mice that did not suffer from pyometra." (PMID 37923360, 2024). "The ectopic expression of FOXA2 in the endometrium of the mice developing pyometra and their highly reduced gland number are indicators of endometrial epithelium defects, particularly because glands develop by invagination of the endometrial lumenal epithelium." (PMID 37923360, 2024). "To test whether FOXA2 transcriptional activity was elevated in CLCa KO mice, we analysed the expression of FOXA2 target genes including Ltf and Muc1 in the uterus of WT, CLCa KO, and CLCb KO mice and CLCa KO mice with pyometra." (PMID 37923360, 2024). "Analysis of female mice lacking CLCa that developed pyometra revealed ectopic expression of epithelial differentiation markers (FOXA2 and K14) and a reduced number of endometrial glands, indicating defects in the lumenal epithelium." (PMID 37923360, 2024).
renal cell carcinoma (1 paper, 2023). "We showed that FOXA2 activates HIF2α expression to promote renal cell carcinoma progression and is regulated by VHL." (PMID 38072043, 2023). "However, the role of FOXA2 in renal cell carcinoma progression remains unknown." (PMID 38072043, 2023). "To investigate the clinical relevance of FOXA2 expression in renal cell carcinoma, we examined FOXA2 expression in renal tissue microarray (TMA) specimens from a cohort of 75 patients with RCC by immunohistochemistry using a specific anti-FOXA2 antibody." (PMID 38072043, 2023).
rhabdomyolysis (1 paper, 2020). Necrosis or disintegration of skeletal muscle often followed by myoglobinuria. "Thus, FoxA2 most likely ensures that the organism’s daily activities do not trigger rhabdomyolysis." (PMID 32143325, 2020).
squamous cell carcinoma (1 paper, 2018). A carcinoma arising from squamous epithelial cells. "We noted that growth of NCI-H292 cells transfected with FOXA2 siRNA significantly increased compared with controls, suggesting that FOXA2 may be an important regulator for squamous cell carcinoma cell and adenocarcinoma cell proliferation." (PMID 29456509, 2018). "Also, squamous cell carcinomas uniformly lack FOXA2 staining." (PMID 29456509, 2018).
Stroke (1 paper, 2024). Sudden impairment of blood flow to a part of the brain due to occlusion or rupture of an artery to the brain. "However, Foxa2 expression has not been reported in patients with stroke." (PMID 39026989, 2024).
type II citrullinemia (1 paper, 2019). "Furthermore, identification of FOXA2 as specific enhancing protein might be useful as therapeutic target to increase the expression of AGC2 in patients with type II citrullinemia showing a mild phenotype, as reported for other mitochondrial carrier deficiencies." (PMID 30995827, 2019).
uterine cancer (1 paper, 2022). Primary or metastatic malignant neoplasm involving the uterine corpus and/or the cervix. "In contrast to Foxa2, Foxa2/Pten mice developed aggressive bulky uterine cancers by 1 year of age, resulting in greatly accelerated mortality (P < 0.0001, Foxa2/Pten vs. either single KO)." (PMID 35703180, 2022).
tumor (104 papers, 2009 to 2026). "Further bioinformatics analyses and rescue experiments confirmed that FOXA2 mediates the tumor-suppressive effects of LINC00261 while restoring FOXA2 levels reversed the effects of LINC00261 loss." (PMID 40136629, 2025). "Silencing linc00261 induced tumor metastasis through the induction of FOXA2 transcription deficiency in HCC." (PMID 39199296, 2024). "By being additionally linked to several malignancies, FOXA1 and FOXA2 exhibit tumor-type-specific characteristics that depend on specific transcriptome connections." (PMID 37626655, 2023). "Diverse observations in this study, made in humans and mice, combined with previous studies, designate FOXA2 as a tumor suppressor where loss of function promotes endometrial carcinogenesis." (PMID 35703180, 2022). "Initially, prior to the appearance of neoplasms, Foxa2/Pten-deficient but histologically normal glands retained ERα and PR, whereas invasive cancers in animals at 12 months of age showed ERα/PR loss, similar to the loss of ERα/PR in human ECs." (PMID 35703180, 2022). "The dearth of recurring mutations in FOXA2 is consistent with our finding that FOXA2 is a tumor suppressor." (PMID 35703180, 2022). "Mutations occurred across the coding region, suggesting that in the endometrium, FOXA2 functions as a tumor suppressor where loss of activity drives tumorigenesis." (PMID 35703180, 2022). "FOXA2 remained significantly associated to the mucinous nature of the tumor after multi‐testing correction." (PMID 33356003, 2021). "The expression of GNG8, MYO1H, and TNFRSF13B was significantly down-regulated, while the expression of SYT14 and FOXA2 was significantly up-regulated in the samples with higher tumor stage, the samples with high risk had lower overall survival rates." (PMID 34322156, 2021). "Pathway analysis showed activation of the transforming growth factor-β pathway in YSTs, which is associated with the overexpression of GATA6 and FOXA2 and the hypermethylation of tumor-suppressor genes (e.g., RASSF1, RUNX3, HIC1, or APC)." (PMID 32999426, 2020). "Given that FOXA2 exerts essential roles in these processes, the loss or gain of FOXA2 function can modify the tumor biological behavior and participate in tumorigenesis." (PMID 31007610, 2019). "Univariate and multivariate analyses showed that low FoxA2 expression was associated with tumor relapse and survival." (PMID 31689237, 2019). "For example, does dysregulation of TCF7L1/FOXA2 lead to loss of differentiated features, a hallmark of anaplastic tumours?" (PMID 26675138, 2016). "By contrast, loss of Foxa2 expression characterized invasive tumor cells that showed definitive signs of EMT." (PMID 26395490, 2015). "However, sexually dimorphic HCC was completely reversed in FOXA1- and FOXA2-deficient mice, with tumor volume becoming larger in FOXA1- and FOXA2-deficient female mice, and conversely, tumor volume was decreased in male mice." (PMID 38605023, 2024). "The tumor suppressive activity of FoxA2 is associated with its induction of Dkk1, Cu12 and Cdc73." (PMID 37298091, 2023). "Notably, loss of Foxa2 expression was evident in edge cells of E-cadherin+ tumor nests (C′)." (PMID 26395490, 2015). "The authors revealed that LINC00261 recruits SMAD3 to the promoter region of FOXA2 (Forkhead Box A2), a neighboring tumor suppressor gene, thereby activating its expression." (PMID 40136629, 2025). "Mechanistically, tumor cells with a tendency for brain metastasis can inhibit 4-aminobutyrate aminotransferase (ABAT) by downregulating forkhead box A2 (FOXA2) expression, leading to increased GABA accumulation." (PMID 39972344, 2025). "The research also discovered that CUR increases the expression of Forkhead box transcription factor A2 (FOXA2) or hepatocyte nuclear factor 3 beta, a suppressor of tumor metastasis in human lung malignancies." (PMID 40860906, 2025).